FGFR4 (fibroblast growth factor receptor 4)
Diseases named in the same sentence as FGFR4 in open-access papers (continued):
Sharing a sentence is not in itself a finding about the gene and the disease.
breast cancer (continued). "In the METABRIC dataset, breast cancer patients (no particular subtyping) with high FGFR4 expression or amplified FGFR4 exhibited a significantly worse overall survival compared to breast cancer patients with unaltered FGFR4." (PMID 34344433, 2021). "Since FGFR4 knockdown in MDA-MB-468 and HCC1937 decreases AKT phosphorylation, and AKT is known to play an essential role in cell survival, we postulate that AKT hyperactivation may sustain the survival of these breast cancer cells." (PMID 27192118, 2016). "In breast cancer, FGFR4 was overexpressed in 33% of HER2-enriched tumors (PAM50 classified, n = 58), and significantly associated with poorer overall survival compared with the non-overexpressing group (P = 0.044; FGFR4 overexpression in 4% of all breast cancers; n = 825)." (PMID 30903103, 2019). "Finally, to determine whether FGFR4/FGF19 co-expression is present in primary breast tumors, we stained tissue microarrays of primary human breast cancer samples diagnosed with invasive ductal carcinoma (IDC) for FGFR4 and FGF19, and compared this with AKT phosphorylation." (PMID 27192118, 2016). "Other genes, including ATP5A, BCR, FGFR4, PDPK1, PIP5K1C, RIOK3, and SRC, also act to regulate TRAIL-induced apoptosis, but their potential to overcome resistance to TRAIL-induced cytotoxicity when inhibited may be more context specific (that is, in a more-restricted subset of breast cancer cells)." (PMID 24745479, 2014). "A negative correlation between FGFR4 expression and YTHDC2 levels was observed in the TCGA cohort of HER2-positive breast cancer patients." (PMID 35562334, 2022). "Depletion of endogenous FGFR4 induces tumor-specific lethality in MDA-MB-468 and HCC1937 basal-like breast cancer cells but not in the MCF-7 luminal-like breast cancer cells nor in SKBR3 HER2-positive cells." (PMID 27192118, 2016). "FGFR4 is absent in normal differentiated muscles and is specifically overexpressed in RMS, as well as in other tumors, such as hepatocellular carcinomas, head and neck squamous cell carcinomas and basal-like breast cancer." (PMID 33182650, 2020). "FGFR4-induced genomic signature was also found to be predictive of organ-specific metastases (brain, liver, lung) in the Molecular Taxonomy of Breast Cancer International Consortium (METABRIC) breast cancer patient cohort independent of clinical subtype or stage." (PMID 35193394, 2022). "Inhibition of FGFR4/FGF19 autocrine axis enhances doxorubicin, but not cisplatin or paclitaxel, sensitivity in MDA-MB-468 and HCC1937 breast cancer cells, suggesting that the anti-FGF19 monoclonal antibody might potentiate sensitivity of refractory tumor cells to chemotherapy." (PMID 27192118, 2016).
hepatocellular carcinoma (94 papers, 2010 to 2026). A malignant tumor that arises from hepatocytes. "FGFR4 is frequently overexpressed in cancers, and it is prone to hotspot activating mutations in breast cancer and hepatocellular carcinoma, among others." (PMID 39576839, 2024). "FGFR4 gatekeeper mutations V550L/V550M have been reported in patients with hepatocellular carcinoma after treatment with BLU-55428." (PMID 36697561, 2022). "FGF15/19 signaling has been implicated in the development of hepatocellular carcinoma, making FGFR4 antagonists attractive candidates for treating this disease." (PMID 34362888, 2021). "Moreover, CSCs can undergo epithelial-mesenchymal transition (EMT), and FGF19/FGFR4 signaling has been implicated in this process in colorectal cancer and hepatocellular carcinoma." (PMID 33066597, 2020). "However, the molecular mechanisms underlying FGF19/FGFR4 signaling in the antitumor effects to MKIs in hepatocellular carcinoma (HCC) remain unclear." (PMID 33674622, 2021). "Recently, FGF19/FGFR4 was reported to cause hepatocellular carcinoma (HCC) in mice, providing further insights into the pathogenesis of the disease in humans." (PMID 27029060, 2016). "Human fibroblast growth factor 19 (FGF19), its receptor (FGFR4) and EpCAM play an important role in cell proliferation, differentiation, motility, and overexpression have been linked to hepatocellular carcinoma (HCC)." (PMID 27447573, 2016). "Targeting these regulatory axes holds promise for controlling FGFR4-driven tumor metastasis, particularly in gastrointestinal and hepatocellular carcinoma malignancies." (PMID 41584352, 2026). "Encouraging results from trials have been reported for FGFR4-specific inhibitors in patients with hepatocellular carcinoma." (PMID 40393028, 2025). "FGFR4, the key functional receptor of FGF17, is overexpressed in several cancers, including NSCLC, colorectal, breast, and hepatocellular carcinoma, and is closely linked to unfavorable patient outcomes." (PMID 41551579, 2025). "Overall, MFCD00832235 and MFCD00204244 demonstrated to be potential FGFR4 inhibitors, particularly for the treatment of hepatocellular carcinoma." (PMID 40547312, 2025). "Multiple phase 1 and phase 2 clinical trials are currently underway using select small molecule inhibitors of FGFR4 in cancers such as hepatocellular carcinoma and acute myeloid leukemia." (PMID 39576839, 2024). "Expression of FGFR1 and FGFR4 was generally very low in keratinocytes in comparison to human primary fibroblasts (HPF) or HepG2 hepatoma cells, respectively." (PMID 39340759, 2024). "In another study, hepatoma cell lines treated with FGF19 (a specific FGFR4 agonist) showed reduced cell proliferation and invasion." (PMID 38540215, 2024). "F30, a FGFR4-targeting compound, induces ferroptosis in hepatocellular carcinoma cells by dysregulating iron levels and redox balance, with its effects dependent on HMOX1." (PMID 39315094, 2024). "Subsequent studies have demonstrated the potential of FGFR4 as a therapeutic target in BC and hepatocellular cancer." (PMID 39234247, 2024). "A subset of human hepatocellular carcinomas is driven by abnormal signaling through FGF19 and its receptor FGFR4, which is associated with poor prognosis." (PMID 37108717, 2023). "Fibroblast growth factor receptor 4 (FGFR4) is a promising target for the treatment of hepatocellular carcinoma, but current FGFR4 covalent inhibitors target only one of the two cysteine residues (Cys477 or Cys552) that provide FGFR4-specificity." (PMID 36697897, 2022). "The fibroblast growth factor 19 (FGF19)/fibroblast growth factor receptor 4 (FGFR4) signaling pathways play critical roles in a variety of cancers, such as hepatocellular carcinoma (HCC)." (PMID 36697897, 2022).
hepatocellular carcinoma (continued). "Aberrant FGF19/FGFR4 signaling pathways (i.e., amplification, mutation, rearrangements, or overexpression) have been detected in a variety of cancers, such as hepatocellular carcinoma (HCC), breast cancer, prostate cancer, and pancreatic cancer." (PMID 36697897, 2022). "Roblitinib demonstrated promising clinical efficacy and a favorable safety profile in phase II clinical trials for the treatment of hepatocellular carcinoma and solid tumors with high FGFR4 expression." (PMID 35562334, 2022). "Gao and co-workers demonstrated that FGF19/FGFR4 signaling in hepatocellular carcinoma (HCC) cells is one of the main resistance mechanisms to sorafenib, a multikinase inhibitor inducing the ROS (reactive oxygen species)-associated apoptosis." (PMID 34830951, 2021). "More importantly, FGF19 signaling through the FGFR4/β-klotho receptor complex has been shown to be a key driver of growth and survival in hepatocellular carcinoma, which makes selective FGFR4 inhibition an attractive therapeutic opportunity." (PMID 33935756, 2021). "With the coaction of KLB, FGFR4 initiates a growing number of intracellular signaling pathways to target tumor cells, promoting hepatoma cell proliferation and migration and inhibiting tumor cells apoptosis." (PMID 33802841, 2021). "At present, FGF401 is in clinical phase I/II trials for hepatocellular carcinoma patients with FGF19/FGFR4 signal abnormity." (PMID 33568192, 2021). "We also evaluated the in vivo efficacy of SHP099 on an FGFR4-dependent patient-derived hepatocellular carcinoma xenograft HCC09-0913." (PMID 32076487, 2020). "The selective FGFR4 inhibitor BLU9931 that was used in this study can inhibit FGF19/FGFR4-positive hepatocellular carcinoma tumors." (PMID 33066597, 2020). "Recently, our group investigated the role of FGF8, FGF18, and FGFR4 in colo-(rectal) and hepatocellular cancer." (PMID 31527546, 2019). "In hepatocellular carcinoma samples, FGFR4 expression was found to be increased alongside the expression of TGFβ, suggesting that an increase in expression contributes towards fibrosis." (PMID 30589872, 2018). "FGF19 specifically binds FGFR4 and high FGF19 expression or hyperactivation of FGF19/FGFR4 signalling in hepatocellular carcinoma (HCC) cells is responsible for the resistance to sorafenib, the only TK inhibitor approved for the treatment of this diseases." (PMID 30423915, 2018). "The fibroblast growth factor receptor 4 (FGFR4) pathway is an essential regulatory component of bile acid synthesis, and its relationship with hepatocellular carcinoma (HCC) has been reported." (PMID 28445152, 2017). "For instance, BLU9931, an irreversible inhibitor of FGFR4, has been developed as targeted therapy for patients with FGFR4-actvated hepatocellular carcinoma." (PMID 27029060, 2016). "This study helps to elucidate a relationship between FGF19 and its respective receptor FGFR4 in the promotion of hepatic stem cells as indicated by increased EpCAM within the carcinogenesis sequence of fatty liver to hepatocellular carcinoma in the specimens." (PMID 27447573, 2016). "This protein is often deleted in hepatocellular carcinomas and the results suggest that the interaction of βklotho and FGFR4 suppress proliferation of neoplastic hepatocytes." (PMID 24743506, 2014). "We investigated human FGF19 and FGFR4 expression in 40 hepatocellular carcinoma specimens using quantitative real-time reverse transcription polymerase chain reaction (RT-PCR) analysis and immunohistochemistry." (PMID 22309595, 2012). "In this study, we provide evidence that FGFR4 participates in hepatocellular carcinoma and that treatment with an FGFR4 inactivating antibody can provide anti-tumor benefits." (PMID 22615798, 2012). "Repression of KLB expression suppressed FGFR4 downstream signaling and significantly inhibited hepatoma cell proliferation." (PMID 22439738, 2012).
hepatocellular carcinoma (continued). "Using immunohistochemistry we localized FGFR4 in a panel of lung, breast, pancreas, and ovarian adenocarcinomas, lung squamous cell carcinoma, hepatocellular carcinoma, thyroid carcinoma, and normal lung, pancreas, and thyroid samples." (PMID 22615798, 2012). "Radio-iodinated FGF19 exhibited an affinity with a Kd value of 303 pM to the FGFR1-KLB complex expressed on the T-Rex 293 cells, and 778 pM to a hepatocellular carcinoma cells expressing FGFR4 and KLB." (PMID 22442730, 2012). "Furthermore, a positive feedback loop involving FGF19, HOXB5, and FGFR4 has been identified in hepatocellular carcinoma, further amplifying oncogenic signaling." (PMID 41584352, 2026). "However, increased levels of FGFR4 expression have been detected in various cancers, such as breast cancer, hepatocellular carcinoma, renal cell carcinoma, lung cancer, and pancreatic cancer." (PMID 40547312, 2025). "Overall, this study suggested that MFCD00832235 and MFCD00204244 were potential FGFR4 inhibitors and may serve as start points for developing novel modulators of FGFR4 for cancer treatment, particularly hepatocellular carcinoma." (PMID 40547312, 2025). "Additionally, FGF19 is linked to the progression of hepatocellular carcinoma, and FGF23 mediates its effect by activating FGFR1c, FGFR3c, FGFR4, and the α-Klotho cofactor." (PMID 37108717, 2023). "Moreover, an antibody blocking the interaction of FGF19 to FGFR4 limited the formation of colon tumor xenografts in vivo, preventing hepatocellular carcinomas in FGF19 transgenic mice." (PMID 37108717, 2023). "FGF19 amplification-induced FGFR4 activation was observed in hepatocellular carcinomas and might represent FGFR4-dependent cancer subtype 1,2,8-10." (PMID 36168616, 2022). "It has been reported that activation of Nrf2 inhibited NAFLD and NASH through upregulating heme oxygenase-1 (HO-1) /NAD(P)H:quinone oxidoreductase 1 (NQO1)/glutathione S-transferase (GST), then promoted hepatocellular carcinoma by competing with Keap1 or through FGFR4–GSK3β signal pathway." (PMID 33114130, 2020). "Increased FGFR4 mRNA expression has been detected in one-third of hepatocellular carcinoma (HCC)." (PMID 30634399, 2019). "Moreover, although FGF19 has minimal mitogenic activity in fibroblasts in vitro, the skeletal muscles of FGF19 transgenic mice develop hepatocellular carcinoma in a manner dependent on FGFR4 expression." (PMID 31408968, 2019). "Our previous study revealed that FGFR4 rs351855 might be related with the risk of hepatocellular carcinoma (HCC) associated with liver cirrhosis and might increase the alpha-fetoprotein level in Taiwanese patients with HCC." (PMID 29221201, 2017). "FGF401 (Novartis) is a tyrosine kinase inhibitor with high selectivity against FGFR4 compared to FGFR1-3 and is under investigation in a phase I/II study in patients with hepatocellular carcinoma with FGFR4 and Klothoβ expression (ClinicalTrials.gov Identifier: NCT02325739)." (PMID 28943626, 2015). "Indeed, in a recent report, it has been described that targeting FGFR4 with an specific monoclonal antibody inhibited hepatocellular carcinoma growth in a mouse xenograft model." (PMID 23696849, 2013). "Moreover, we examined the expression and the distribution of FGF19 and FGFR4 in 5 hepatocellular carcinoma cell lines (HepG2, HuH7, HLE, HLF, and JHH7) using RT-PCR and immunohistochemistry." (PMID 22309595, 2012). "Hence, we are able to examine the effects of KLB perturbation in an aggressive hepatoma model driven by elevated FGFR4 activity." (PMID 22439738, 2012). "In particular, our results suggest that FGFR4 may play an important role in hepatocellular carcinoma." (PMID 22615798, 2012). "FGFR4 overexpression has been reported in several solid tumors, including hepatocellular carcinoma (HCC), oropharyngeal squamous cell carcinoma, breast cancer, and pancreatic cancer." (PMID 36622048, 2023).
hepatocellular carcinoma (continued). "The FGF19/FGFR4 signaling pathway dysregulation is widely detected in many types of diseases including cancers, especially in hepatocellular carcinoma (HCC)." (PMID 34576070, 2021). "FGF19 is however, also a strong inducer of liver carcinomas in mice and it is of high importance to mitigate the mitogenic, FGFR4-mediated effect of FGF19 to allow human therapy, even though species difference may indicate that FGF19 is less mitogenic in human cellular systems." (PMID 33414764, 2020). "In other words, higher FGFR4 expression results in worse prognosis and its inhibition reduces hepatocellular carcinoma (HCC) aggressiveness." (PMID 32555680, 2020). "This is the first study to elucidate FGF19/FGFR4 signaling in favor of HCC cells developing as indicated by increased EpCAM within the carcinogenesis sequence from fatty liver to hepatocellular carcinoma." (PMID 27447573, 2016). "To test the importance of FGFR4 in hepatocellular carcinoma, we evaluated the effect of its ablation in a genetically engineered mouse model of HCC and assessed the effects of therapeutic FGFR4 neutralization in relevant mouse tumor models." (PMID 22615798, 2012). "We had previously demonstrated overexpression of fibroblast growth factor receptor-4 (FGFR4) in hepatocellular carcinoma (HCC)." (PMID 22439738, 2012). "In hepatocellular carcinoma (HCC), abnormal expression and activation of FGFR4 are closely related to tumor proliferation, invasion and metastasis." (PMID 40547312, 2025). "In hepatocellular carcinoma, the FGF19/FGFR4 axis was reported to be an oncogenic driver pathway, suggesting it as a promising target." (PMID 38273381, 2024). "FGFR4-selective inhibitors have been tested in clinical trials of patients with hepatocellular carcinoma (HCC), but the patient response to FGFR4-selective inhibitors in HCC appeared to be unsatisfactory." (PMID 37817227, 2023). "In a phase 1 trial of Fisogatinib, a type 1 irreversible inhibitor of FGFR4, an overall response rate (ORR) of 17% and median duration of response (DOR) of 5.3 months were achieved in patients with hepatocellular carcinoma." (PMID 37888109, 2023). "It has been previously reported that hFGF19/FGFR4 signaling leads to the activation of Ras-Raf-Erk1/2 MAPK pathway, and thus functional assay for recombinant scvhFGF19 is conducted using HepG2 hepatocellular carcinoma cell line." (PMID 33297586, 2020). "In hepatocellular carcinoma cells, the FGF19/FGFR4 axis has been shown to upregulate ERK/AKT–p70S6K–S6 pathway." (PMID 32111983, 2020). "The FGF19/FGFR4 axis has also been reported to induce mTORC1 and ERK pathways to converge on S6 in hepatoma cells and in head and neck squamous cell carcinoma (HNSCC)." (PMID 32111983, 2020). "This review aims to describe the role of the FGF19/FGFR4 pathway in hepatocellular carcinoma and its role as a potential predictive biomarker for novel targeted agents against FGF19/FGFR4 signalling." (PMID 28943626, 2015). "Furthermore, FGFR4 is a driving oncogene in a subset of hepatocellular carcinomas in which FGF19, a unique ligand of FGFR4, is amplified." (PMID 40731412, 2025). "MiR-486-3p inhibits the proliferation, migration, and invasion of retinoblastoma, inhibits the proliferation and metastasis of cervical cancer, targets FGFR4 and EGFR to mediate drug resistance in hepatocellular carcinoma, and reverses the malignant phenotype of GBM cells." (PMID 38725030, 2024). "Given that FGFR4 inhibitors are currently in early-stage clinical trials for treatment, this protein, a target of autoantibodies, is of interest as a druggable target in BC, CRC, and hepatocellular cancers." (PMID 39234247, 2024). "A pre-clinical study suggested that βKlotho mediates FGF9 pro-survival functions in hepatocellular carcinoma via FGFR3 and FGFR4 and may be useful in selecting patients who could benefit from anti-FGFR therapies." (PMID 37958253, 2023).